IL13RA1 (interleukin 13 receptor subunit alpha 1)
Diseases named in the same sentence as IL13RA1 in open-access papers (continued):
Sharing a sentence is not in itself a finding about the gene and the disease.
cancer (24 papers, 2010 to 2023). A tumor composed of atypical neoplastic, often pleomorphic cells that invade other tissues. "These clinical impact of the IL4Rα and IL13Rα1 expression in human cancer has been associated with the role of IL4Rα/IL13Rα1 receptor complex in the proliferation and survival of cancer cells." (PMID 33419470, 2021). "The individual and co-expression patterns of IL4Rα and IL13Rα1 were significantly associated with cancer-specific survival (CSS) and relapse-free survival (RFS) in univariate analysis." (PMID 31540495, 2019). "It has been reported that receptors for IL4 and IL13 (IL4Rα or IL13Rα1) in several type of cancers is associated with poor prognosis and thus could be therapeutic targets of cancer treatment." (PMID 35207737, 2022). "Transcriptional analysis of correlation patterns was conducted on clinical samples from CRC patients to reveal possible association between expression level of IL4, IL4Ra, IL13, and IL13Ra1 and that of representative mediators/markers associated with cancer development and progression." (PMID 32512917, 2020). "We, in turn, observed IL13Ra1 in tumors to correlate positively with expression of genes encoding proteins involved in promoting cancer, especially those facilitating invasion and metastasis such as α smooth muscle actin, HIF1α, and VEGF-A, although not with proliferation marker Ki67." (PMID 32512917, 2020). "In conclusion, IL13-mutein CAR T cells show improved selectivity for IL13Rα2-expressing cancer cells relative to IL13Rα1-expressing tumors." (PMID 35939683, 2022). "Several human cancer cell lines with varying expression of IL13Rα1 were used to evaluate relative effector activity of IL13 WT and IL13-variant CAR T cells." (PMID 35939683, 2022). "In line with this study, the role of the expression of IL4Rα and IL13Rα1 as prognostic indicator has been reported in various human cancers." (PMID 35207737, 2022). "The results of long-term killing assays against IL13Rα1-expressing cancer cell lines mirrored those of the degranulation and cytokine production assays: C4 and D7 CAR T cells showed diminished killing relative to WT and E12Y." (PMID 35939683, 2022). "The cut-off points have the highest area under the curve (AUC) to predict cancer-related death of patients, and the cut-off points for Nu-IL4Rα, Cy-IL4Rα, Nu-IL13Rα1, and Cy-IL13Rα1 were 8, 11, 9, and 14, respectively." (PMID 35207737, 2022). "In vitro and in vivo functional characterization of C4 and D7 IL13-mutein CAR T cells showed decreased activation, degranulation, cytokine release, and cytolytic activity compared to WT and E12Y CAR T cells in the presence of IL13Rα1-expressing cancer cells." (PMID 35939683, 2022). "We determined the role and expression of IL13Rα1 in PCa cancer cells using western blotting, flow cytometry, and cell proliferation assays." (PMID 34652890, 2021). "The prognostic impact of the expression of IL4Rα and IL13Rα1 in human cancers is related to the role of IL4Rα/IL13Rα1 in cancer-related signaling." (PMID 33419470, 2021). "Recently, IL4Rα and IL13Rα1 were reported to have roles in cancer progression and suggested as potential prognostic markers." (PMID 33419470, 2021). "Higher expression of IL4Rα and IL13Rα1 was observed in various types of human cancers such as colorectal, breast, pancreatic, bladder, brain, and ovarian cancers." (PMID 33419470, 2021). "The activation of IL4Rα/IL13Rα1 by IL4/IL13 stimulates JAK1/JAK2/JAK3-STAT6-mediated proliferation of cancer cells." (PMID 33419470, 2021). "A study reported that the interactions between interleukin-13 and interleukin-13 receptor alpha 1 (IL13RA1) contributed to cancer cell growth and metastasis, and IL13RA1 expression was associated with poor prognosis in invasive BC patients." (PMID 33489894, 2020). "Remarkably, D1 not only blocked IL-13 binding to IL13Rα2, but also inhibited IL13Rα1-mediated STAT6 activation in both cancer types." (PMID 30318506, 2018).
cancer (continued). "The mRNA for IL-13Rα1 was expressed at low levels and its expression was similar in all stages of cancer." (PMID 25208941, 2014). "Interestingly, C4, but not D7, showed attenuated cytotoxicity relative to WT against IL13Rα1/IL4Rα-coexpressing cancer cells in vitro and in vivo." (PMID 35939683, 2022). "Studies that have investigated the role of IL-13Rα1 in cancer are conflicted." (PMID 33591997, 2021). "In addition, the prognostic significance of individual expression of IL4Rα or IL13Rα1 has been reported in various human cancers." (PMID 33419470, 2021). "Therefore, further study is needed to clarify the role of cytoplasmic and nuclear expression of IL4Rα and IL13Rα1 in human cancers." (PMID 33419470, 2021). "IL4 and IL13 bind to IL4Rα and IL13Rα1 chains, forming functional structures in cancer cells." (PMID 31540495, 2019). "Interestingly, coexpression of IL13Rα1 or IL4Rα in cancer cells caused both E12Y and D7 CAR T cells, but not C4 CAR T cells, to respond comparably to WT CAR T cells in vitro." (PMID 35939683, 2022). "Thus, not only the distinct expression levels of respective receptor chains, but also the ratio between IL-13Rα1 and IL-4Rα expression may be crucial for the effect of IL-4 and IL-13 on the cancer cell phenotype." (PMID 35409019, 2022). "Therefore, it is suggested that the nuclear localization of IL4Rα and IL13Rα1 might have a role in the progression of cancers." (PMID 33419470, 2021). "Therefore, targeting the IL4R complex might be a therapeutic strategy for cancers with poor prognosis that highly express IL4Rα and IL13Rα1." (PMID 33419470, 2021). "Therefore, IL4Rα and IL13Rα1 might be an effective therapeutic target of various human malignant tumors." (PMID 31540495, 2019). "Specifically, exposure of rats to PM2.5–10 from LAC for 1–3 months was found to trigger the expression of inflammatory stress- and cancer-related biomarkers, including upregulation of IL16, IL13-Rα1, and EGR2 genes in the brain." (PMID 32211584, 2020). "The addition of both E12K and R109K mutations into an IL13-based CAR also showed attenuated, but not abolished, recognition of IL13Rα1-expressing cancer cells relative to IL13Rα2-expressing cancer cells." (PMID 35939683, 2022). "Although IL-13Rα1 is expressed at basal levels and uniformly in a variety of cancer and non-cancer cells and tissues, IL-13Rα2 is predominantly overexpressed in a variety of solid cancers and inflammatory pathologies." (PMID 34201539, 2021). "Unlike the other IL-13 receptor, IL-13Rα2, data on IL-13Rα1 in the GIT cancers are limited and inconclusive." (PMID 32512917, 2020). "Thus, by Western blot and immunoblot analysis, it was reported in CRC samples a positive correlation between IL-13Rα1 and ZEB1 probably demonstrating that IL-13/IL-13Rα1/STAT6/ZEB1 axes promote EMT and aggressiveness of this cancer." (PMID 31781477, 2019). "Whereas D1 peptide inhibited IL-13-mediated invasion in IL13Rα1-silenced or control cells in both types of cancer, Rα1 peptide did not." (PMID 30318506, 2018). "IL-13Rα1 was weakly expressed in both cancer and normal cell lines and IL-2RγC chain was absent in these samples." (PMID 25208941, 2014). "Interestingly, effector activity of D7 CAR T cells, but not C4 CAR T cells, was demonstrated when cocultured with IL13Rα1/IL4Rα-coexpressing cancer cells." (PMID 35939683, 2022). "However, the low micromolar affinity was not sufficient to decrease D7 CAR T cell response to IL13Rα1/IL4Rα-overexpressing cancer cells." (PMID 35939683, 2022). "In addition, based on the molecular relationship between IL4Rα and IL13Rα1 as components of the type II IL4R complex and their possible roles in cancer progression, we evaluated the prognostic significance of the co-expression pattern of nIL4Rα and nIL13Rα1 in STSs." (PMID 33419470, 2021).
cancer (continued). "However, despite the presence of cytoplasmic and nuclear expression of IL4Rα and IL13Rα1 in human cancers, there have been no reports specifically focused on the effects of subcellular localization of IL4Rα and IL13Rα1 in human cancers." (PMID 33419470, 2021). "However, the significance of the nuclear localization of IL4Rα and IL13Rα1 in the progression of cancer is not clear." (PMID 33419470, 2021). "IL13Rα2 expression is specific for cancer cells while IL13Rα1 is not." (PMID 30318506, 2018). "Expression of other receptor molecules (IL13RA1, IL15RA, IL22RA1 and IFNGR1/2) was increased in carcinoma tissue, however due to our FC restriction we did not test these mRNAs for associations with miRNA differential expression." (PMID 30603058, 2018).
infection (14 papers, 2009 to 2025). The state of being infected such as from the introduction of a foreign agent such as serum, vaccine, antigenic substance or organism. "In our study, pSTAT6, IL-4Rα, and IL-13Rα1 were significantly increased following infection with S. japonicum." (PMID 31886304, 2019). "Down-regulation of Il13ra1 combined with up-regulation of Il12b (30.2-fold), suggested switch to a pro-inflammatory response by 4 hrs post H37Rv-infection." (PMID 22039457, 2011). "Of note, IL-13Rα1 but not IL-4Rα mRNA levels were decreased upon Elp3 deficiency 7 days post-infection." (PMID 39085648, 2024). "Six genes belonging to the two most significantly over-represented biological processes at the 15 min post H37Rv-infection ‘Immune system response’ (Ifnb1, Il12b, Ccl24, Pparg, and Clec4a2) and ‘Response to stimulus’ (Il13ra1) were selected for verification by RT-QPCR analysis." (PMID 22039457, 2011). "The upregulation of IL13RA1, OSMR, CRLF2, and IL6R in our study may indicate responses to maintain neuromuscular integrity under infection-induced stress." (PMID 40943072, 2025). "Thus, we found significant interactions of diet and infection for several genes, especially those related to the mucosal barrier, such as DCLK1, HDAC9, IL13RA1, MUC2 and HDAC1 (Fold change 2.5, 1.9, 1.3, 1.3 and − 1.2, respectively)." (PMID 38081984, 2023). "Furthermore, we observed that IL-13Rα1 and IL-13 receptor were down-regulated in HBAAV2/9-Sja-miR-71a-treated schistosome-infected livers compared to schistosome-infection control groups." (PMID 32944173, 2020). "However, expression of Alox12, Alox12e, Alox8, Alox12b, Il13rα1, Il4rα, Il2rg, and Il13 were not altered following Hpb infection." (PMID 40490052, 2025). "The Ifnb1 and Il13ra1 genes were not significantly differentially expressed compared to the uninfected pooled common reference at any of the time-points following H37Rv-infection." (PMID 22039457, 2011). "An up-regulation of the transcription of the IL-13 receptor (Il13ra1) was observed by 15 min post Δ-mce1 H37Rv-infection however, a corresponding change in the concentration of IL-13 measured in the supernatant could not be detected during the first hour post Δ-mce1 H37Rv-infection." (PMID 22039457, 2011).
cardiovascular disease (1 paper, 2023). "Future studies should focus on a direct comparison of IL-4 and IL-13 as well as their cytokine-specific receptor subunits (i.e., IL-2Rγ and IL-13Rα1, respectively) in the context of cardiovascular disease in vivo to validate the therapeutic potential of targeting one cytokine over the other." (PMID 37949903, 2023).
heart disease (1 paper, 2017). "A deeper understanding of the role of IL‐13Rα1 in heart disease may ultimately pave the way for the development of effective treatment for adverse heart remodeling and failure." (PMID 28528324, 2017).
IL13RA1 also shares sentences with these, for which no sentence is quoted: melanoma (3 papers); adenocarcinoma (2); atopic dermatitis (2); squamous cell carcinoma (2); Anxiety (1); autoimmune encephalitis (1); bacterial infection (1); basal cell carcinoma (1); bladder cancer (1); bladder tumor (1); carotid arterial thrombosis (1); chronic GVHD (1); diabetic cardiomyopathy (1); eosinophilia (1); eosinophilic esophagitis (1); experimental autoimmune encephalomyelitis (1); fibrosarcoma (1); gastric cancer (1); gastrointestinal disease (1); Hepatic (1); Hyperglycemia (1); immune deficiency (1); intestinal tumors (1); keloid (1); lymphomatous (1); malignant glioma (1); myocarditis (1); myopathy (1); neurodegenerative disease (1); Obesity (1).
A further 10 diseases each share a sentence with IL13RA1 in 1 paper.